WARS2-IT1 (WARS2 intronic transcript 1)
Gene: Long non-coding RNA gene on chromosome 1 (119,047,405 to 119,064,785, forward strand). Ensembl gene ENSG00000224238.
Diseases named in the same sentence as WARS2-IT1 in open-access papers:
WARS2-IT1 is named in the same sentence as 1 disease in open-access papers, as found by Europe PMC text mining. Sharing a sentence is not in itself a finding about the gene and the disease. The quoted sentences say what the papers report.
tumor (1 paper, 2025). "Through long noncoding RNA (lncRNA) profiling of tumor cells treated with CAF-conditioned medium (CAF-CM), we identify WARS2-IT1 (WARS2 intronic transcript 1), whose expression is directly stimulated by TGF-β1 signaling." (PMID 41213902, 2025).